FH (fumarate hydratase)
Diseases named in the same sentence as FH in open-access papers (continued):
Sharing a sentence is not in itself a finding about the gene and the disease.
tumor (continued). "Given that FH mutations have been associated with hematopoietic abnormalities and tumor formation, here, we investigated the role of Fh1 in normal and malignant hematopoiesis." (PMID 28202494, 2017). "In SDH and FH-deficient tumours, it was subsequently shown that the massive accumulation of their respective substrates, namely succinate and fumarate is responsible for the inhibition of PHD activity, also leading to a pseudohypoxic response." (PMID 28471419, 2017). "Targeted next-generation sequencing revealed that FH mutation and loss of the second allele were completely identical between blood and tumor samples, suggesting that FH mutation plays a direct role in FH-deficient RCC." (PMID 26983443, 2016). "The oncometabolites succinate and fumarate, which both accumulate due to mutations inactivating SDH or FH, inhibit HIF1α degradation, so causing pseudo-hypoxia and favouring tumour progression." (PMID 27083002, 2016). "Although NRF2 activation has been previously reported as pro-tumorigenic event, its role in FH-deficient tumours is still debated." (PMID 27117029, 2016). "Of note, genetic ablation of p21, a major player in senescence induction, induces transformation of benign cysts in FH-deficient mice indicating the tumour-suppressive role of senescence in FH-mediated tumorigenesis." (PMID 27117029, 2016). "We also investigated FH mutations by sequencing the coding exons and intron flanking regions in both blood and tumor samples by targeted next-generation sequencing analysis." (PMID 26983443, 2016). "In HLRCC-associated tumours, the somatic inactivation of the remaining FH allele causes functional loss of FH leading to abnormal intracellular accumulation of fumarate, resulting in tumourigenesis." (PMID 27144040, 2016). "This post-translational modification is a distinctive feature of FH-deficient tumours and now used for diagnostic purposes." (PMID 27117029, 2016). "This process, called protein succination, is a feature of FH-deficient tumour tissues, where fumarate accumulates to millimolar levels." (PMID 25613188, 2015). "These ‘oncometabolites’ include the tricarboxylic acid cycle metabolites succinate and fumarate, whose levels are elevated in rare tumours with succinate dehydrogenase and fumarate hydratase mutations, respectively." (PMID 25864878, 2015). "A study in five patients with FH-deficient PGL/PCC reported loss of hydroxylation of 5mC in tumor cells." (PMID 26472283, 2015). "Here, we performed a proteomic-based screen using tandem mass spectrometry (MS/MS) to analyse an FH-deficient tumour and two FH-mutant cell lines derived from metastatic renal cancers." (PMID 25105836, 2014). "Tumours derived from SDH or FH mutations are characterised by a strong hypoxic signature and are significantly more vascularised." (PMID 24837709, 2014). "Similar to SDH mutants, a tumor-derived cell line carrying mutations in FH display constitutively elevated ROS levels." (PMID 25126540, 2014). "As for SDHD related tumors, tumor formation in FH heterozygotes is associated with loss of the second allele." (PMID 25126540, 2014). "To further validate synthetic lethality between adenylate cyclase and FH, we used tumor cells harboring a germline mutation in FH, the UOK262 renal tumor cells, a metastatic cell line derived from an HLRCC patient." (PMID 24568598, 2014). "Mitochondrial proteins encoded by tumor-suppressor genes are part of the succinate-dehydrogenase, the fumarate-hydratase, and the mitochondrial isocitrate-dehydrogenase enzymes, all of them participating in the Krebs cycle." (PMID 25126540, 2014). "The primary genetic alteration associated with HLRCC is a germline mutation of the FH gene that encodes fumarate hydratase (FH), which is both a tumor suppressor gene and an enzyme of the Krebs cycle." (PMID 23967283, 2013).
tumor (continued). "The significance of this finding has not been fully elucidated, but the genes encoding succinate dehydrogenase (SDH) and fumarate hydratase (FH) are thought to be major tumor suppressor genes." (PMID 24958263, 2013). "This latter pathway is up-regulated in FH mutant tumor cells and inhibition of heme oxygenase specifically killed FH mutant tumor cells suggesting a novel therapeutic approach to treating cancers with FH mutation." (PMID 24350057, 2013). "One of these variants is the HLRCC syndrome associated with different mutations in the FH gene, which functions as a tumor suppressor gene." (PMID 23320739, 2013). "A relationship between heme synthesis, heme catabolism and FH activity has been identified in tumor cells where loss of FH activity is synthetically lethal with defects in heme catabolism." (PMID 22509282, 2012). "Patients with HLRCC carry heterozygous germline mutations in the gene encoding the Krebs cycle enzyme fumarate hydratase (FH) and tumor formation is associated with loss of heterozygosity at this locus." (PMID 22014577, 2011). "We have previously demonstrated that reintroduction of wild type FH into a FH deficient tumor cell line results in a marked reduction in nuclear HIF-1α levels." (PMID 21695080, 2011). "FH can function as a tumor suppressor: its absence is linked to the formation of human kidney tumors in a syndrome termed HLRCC." (PMID 20231875, 2010). "Although the mechanisms that link SDH and FH mutations to tumour formation are unclear, it is likely that pseudohypoxia is a primary mechanism." (PMID 19778456, 2009). "Both SDH and FH can act as tumour suppressors, and germline mutations in their genes predispose to tumour development." (PMID 19778456, 2009). "Increased succinate or fumarate levels as a consequence of SDH and FH deficiency inhibit hypoxia inducible factor-1α (HIF-1α) prolyl hydroxylases leading to sustained HIF-1α expression in tumours." (PMID 19778456, 2009). "In 84% of the cases, the second allele was inactivated by LOH and the FH gene, therefore, behaved as a classical tumor suppressor." (PMID 19949549, 2009). "In conclusion, FH+ seems to be associated with an asymptomatic diagnosis (and therefore smaller and ER+ tumours), possibly because of the more intensive use of mammography or differences in biological behaviour." (PMID 15162141, 2004). "FH‐deficient RCCs are typically aggressive tumours presenting at high stage." (PMID 41384711, 2026). "Clinical validation confirmed elevated LDHA expression in FH-deficient RCC tumor tissues, which may correlate with immunosuppressive microenvironments and resistance to ICIs." (PMID 41112295, 2025). "This highlights the evolving role of ferroptosis in metastatic progression, where loss of FH activity could provide a survival advantage under the hypoxic and nutrient‐deprived conditions characteristic of secondary tumor sites." (PMID 40919133, 2025). "F1LCDx using circulating‐tumor DNA revealed a possible germline FH mutation; however, because of patient's deteriorating condition, single‐site testing could not be performed while he was alive." (PMID 40034895, 2025). "This aberrant activation of HIF pathways could contribute to tumor growth and survival, providing a crucial link between FH deficiency and oncogenesis." (PMID 40002168, 2025). "As only the tumor cells harbour biallelic FH variant, it is a good candidate for targeted therapy." (PMID 40264827, 2025). "This may be due to the presence of stromal, immune, or other non-tumor cells within the sample, resulting in the FH mutation being detected at only 50%." (PMID 39659780, 2024).
tumor (continued). "Recent investigations into FH-altered RCC have described a notably low tumor mutation burden, distinctive tumor microenvironments characterized by the infiltration of CD8+ T-cells with PD-L1 expression within tumors, and a profoundly depleted and mutated mitochondrial genome." (PMID 38793008, 2024). "However, an additional IHC test for a specific epigenetic marker, 5-hmC, showed the absence of DNA hypermethylation in the tumor and confirmed a different molecular phenotype of the studied FH-mutated tumor." (PMID 38721148, 2024). "The spread of aggressive FH-deficient tumor cells during the procedure could occur, and implantation of metastatic lesions could occur as a direct result of the biopsy procedure." (PMID 39659780, 2024). "FH acts as a tumor suppressor, and the biallelic loss of this gene can cause cancer." (PMID 38721148, 2024). "Moreover, we will discuss the future directions to improve our understanding of FH loss in cancer and potential therapeutic interventions to treat FH-deficient tumours." (PMID 37689804, 2023). "These 2 molecules reliably reflected the FH mutation status and tumor mass." (PMID 37053010, 2023). "The loss of fumarate hydratase in tumor cells leads to the accumulation of fumarate in the TME." (PMID 38139250, 2023). "In addition to its role in energy metabolism, FH has been implicated in the cellular response to DNA double-strand breaks and acts as a tumor suppressor." (PMID 37754259, 2023). "As observed in other diseases such as type 2 diabetes, metformin can be used to re-activate AMPK, and, therefore, could be a promising approach to treat FH-deficient tumours." (PMID 37689804, 2023). "Taking advantage of the robust metabolic rewiring that occurs in FH-deficient cells, we performed plasma metabolomics analysis and identified 2 tumor-derived metabolites, succinyl-adenosine and succinic-cysteine, as excellent plasma biomarkers for early diagnosis." (PMID 37053010, 2023). "Given the regulation at different levels of mTOR, PTEN, and ATF4 in FH-deficient tumours, it is tempting to speculate a potential link between these factors." (PMID 37689804, 2023). "It is possible, therefore, that mutations or loss of mtDNA observed in human lines and patient tissues accrue over several time upon the initial FH loss, and that these defects are selected to induce a more malignant glycolytic phenotype during tumour progression." (PMID 37689804, 2023). "Interestingly, one (sample ULM8.3) out of these five tumours with FH mutations also had a missense mutation, affecting codon 44 in exon 2 of MED12." (PMID 37113812, 2023). "Therefore, improved in vivo models of HLRCC and papillary type 2 renal cancer are needed to ascertain the factors promoting tumour initiation, progression, and permissiveness in FH-deficient tumours." (PMID 37689804, 2023). "Many of the TCA cycle moonlighting enzymes, such as Isocitrate dehydrogenase (IDH) 1 and 2, succinate dehydrogenase (SDH), and fumarate hydratase (FH), which function as tumor suppressors under physiological conditions, have a loss of function mutations in cancer cells." (PMID 36618350, 2022). "While inhibiting fH in patients may not only cause direct cancer cell death, it may also promote an adaptive immune response, important for durable anti-tumor immunity." (PMID 36686777, 2022). "We next explored the relationship between FH expression and tumor mutational burden (TMB) level." (PMID 34737838, 2021). "However, a recent phase 2 clinical trial investigating Guadecitabine (SGI-110) monotherapy (NCT03165721) in patients with SDHx or FH mutated tumours was terminated because of low accrual." (PMID 34834591, 2021). "Thus, it was proposed that the two mechanisms resulting from FH loss can cooperate for tumor progression." (PMID 33233657, 2020). "The diagnosis was confirmed by a loss of FH protein expression in tumor cells." (PMID 32463173, 2020).
tumor (continued). "The FH gene, located on chromosome region 1q42.1, is a tumor suppressor gene that encodes the enzyme fumarate hydratase (fumarase), which plays a role in both the tricarboxylic acid (TCA) cycle in mitochondria, as well as the response to DNA double strand breaks in the nucleus." (PMID 31792767, 2020). "Instead, fumarate hydratase showed immunoreactivity loss in tumor cells." (PMID 32150988, 2020). "Thus, by inhibiting aerobic glycolysis in a HLRCC xenograft animal model, marizomib significantly modulates the metabolism of FH-deficient tumor cells in vivo." (PMID 31804603, 2019). "Thus, loss of FH expression associated with hypoxia-related genes accumulation with consequent tumor cell progression and glycolytic metabolism." (PMID 30986931, 2019). "Interestingly, tumours harbouring mutations in FH were also found to have hypermethylated DNA similarly to the SDHB tumours, in which the epigenetic silencing was particularly severe compared to those tumours with mutations in other SDH subunits." (PMID 29450727, 2018). "The oncogenic role played by changes in mitochondrial metabolism was first spotted by finding that mutations in subunits of SDH, an enzyme placed at the crossroad between OXPHOS and TCA cycle, as well as in the TCA cycle enzyme fumarate hydratase (FH), are causative of some human tumor types." (PMID 30197878, 2018). "We here report the analysis of mutations in genes encoding the metabolic enzymes IDH, SDH and FH in a cohort of ~100 central cartilaginous tumours, and demonstrate that the prevalence of mutations in IDH1 or -2 is ~60%, which is comparable to previously published data." (PMID 28484589, 2017). "Genes encoding succinate dehydrogenase (SDH) and fumarate hydratase (FH) act as tumour suppressors." (PMID 27326424, 2017). "Recently, there are reports showing that the mutation of FH may initiate renal cell carcinogenesis, implying tumor suppressor function of this gene." (PMID 27556703, 2016). "Mutations in IDH, SDH, and FH may interfere with mitochondrial function and respiration in certain rare tumor types." (PMID 26812134, 2016). "Together, these four FH-deficient tumours showed the worst clinical outcome in this cohort." (PMID 27713405, 2016). "The current histological criteria and immunohistochemical markers for FH deficiency (FH and 2SC) appear to be insufficient to reliably distinguish the latter tumour from true HLRCC cases, and it remains critical to recommend genetic counselling when pathologic assessment raises a suspicion of HLRCC." (PMID 27713405, 2016). "Indeed, to address the FH deficiencies in the tumor tissues, we performed immunohistochemistry of FH and HIF1." (PMID 24684806, 2014). "Also, in adult, it has been reported inherited fumarate hydratase mutation which appear to cause tumor growth through activation of the hypoxia pathway." (PMID 25230718, 2014). "Loss of FH activity in HLRCC tumours causes accumulation of the Krebs cycle intermediate fumarate to high levels, which may act as an oncometabolite through various, but not necessarily mutually exclusive, mechanisms." (PMID 25105836, 2014). "Thus, the molecular pathway for tumor growth in FH deficiencies closely resembles VHL deficiency in clear RCCs." (PMID 24684806, 2014). "The intracellular hypoxia inducible factor (HIF) is stabilized due to an accumulation of FH based on the mutations in this gene region and is responsible for a pseudohypoxic state causing the release of different tumor promoting factors like VEGF, PDGF, and TGF-α." (PMID 23320739, 2013). "Finally, analysis of both tumor subtype and FH(+) revealed that 83% (5/6) and 80% (4/5) of patients with FH(+) diagnosed with HR(−) or TN tumors carried a BRCA1 mutation, respectively." (PMID 23469205, 2013). "NRF2 may contribute to tumor development by enabling FH-deficient cells to tolerate high levels of exogenous or endogenous oxidants, thus promoting their survival." (PMID 22866264, 2012).
tumor (continued). "In addition to this study, depicting HIF as a sort of “bystander player” in the onset of tumors harboring FH mutations, another report indicated this transcription factor as a tumor-suppressor protein in tumors carrying IDH1/2 mutations." (PMID 22888353, 2012). "Hence, we conclude that despite the common activation of HIF pathways in VHL- and FH-associated neoplasia, the oncogenic mechanisms are likely to be different." (PMID 22014577, 2011). "Based on these findings, it has been proposed that pharmacological downregulation of HIF pathways by agents that promote HIF hydroxylation in the face of high fumarate levels might provide an effective treatment for FH-associated neoplasia." (PMID 22014577, 2011). "FH expression or binding contributes to protection against C of some pathogenic microbes (e.g., Streptococcus pyogenes, S. pneumoniae, Neisseria gonorrheae, Borrelia sp) and, importantly, of tumor cells." (PMID 18652693, 2008). "Thus, our result is consistent with the heterogeneity of DNA methylation in FH-deficient tumors and may also be related to benign tumor behavior." (PMID 38721148, 2024). "Moreover, the FH mutation may induce excessive free radical generation, thereby promoting cellular oxidative stress, apoptosis, and potentially contributing to tumor development." (PMID 38974045, 2024). "Therefore, mTOR emerges as a potential player in FH-deficient tumours." (PMID 37689804, 2023). "However, if a tumor was determined to be FH-deficient, this would likely prompt early intervention." (PMID 37259915, 2023). "Finally, we also found that FH-deficient tumour tissue exhibited increased levels of interleukin-6 (IL-6), but not IL-10, confirming the presence of an inflammatory milieu in these tumour tissues." (PMID 36890229, 2023). "The loss of function of FH is associated with multiple compensatory metabolic changes, mitochondrial impairment, and the intracellular accumulation of fumarate, as well as an increased sensitivity to DNA damage, which is associated with pseudohypoxia and tumor aggressiveness." (PMID 35205136, 2022). "Moreover, we confirmed PDHA1 phosphorylation in human FH-deficient tumours." (PMID 29191787, 2018). "However, there are a fraction of tumor cells that have been shown to exhibit mitochondrial dysfunction due to loss of function mutations in the TCA cycle enzymes succinate dehydrogenase (SDH) or fumarate hydratase (FH)." (PMID 24917929, 2014). "As highly reducing environment has been shown to stimulate cell proliferation, it is possible to hypothesize that the reduced redox state elicited by FH mutations could favor the doublings of stem-cell-like populations promoting thus the initial event of tumor formation." (PMID 22888353, 2012). "Here, we report a regulation of fumarate hydratase (FH) activity in tumour cells that is mediated by the lysine deacetylase, HDAC6." (PMID 40721560, 2025). "FH is an enzyme of the TCA cycle, and its deficiency or inactivation can lead to significant fumarate accumulation in the tumor stroma." (PMID 40461489, 2025). "Key findings revealed that certain TCA cycle enzymes, such as succinate dehydrogenase (SDH) and fumarate hydratase (FH), act as tumor suppressors, establishing direct links between mitochondrial dysfunction and tumorigenesis." (PMID 40754534, 2025). "Immunohistochemical staining revealed diffuse KRT7, vimentin, PAX8, e-cadherin, SDHA, SDHB and fumarate hydratase expression in tumor cells." (PMID 39980061, 2025). "Altogether, these data illustrate a unique regulation of FH activity in mitochondria of tumour cells by HDAC6 inhibition and that disruption leads to fumarate accumulation, protein succination, and mtROS-dependent cell death." (PMID 40721560, 2025). "In the TCA cycle, succinate dehydrogenase (SDH), isocitrate dehydrogenase (IDH), and fumarate hydratase (FH) are classified as tumor suppressors." (PMID 40137165, 2025).